ALK (ALK receptor tyrosine kinase)
Diseases named in the same sentence as ALK in open-access papers (continued):
Sharing a sentence is not in itself a finding about the gene and the disease.
neuroblastoma (continued). "Finally, alecitinib, a second-generation ALK inhibitor with impressive efficacy and toxicity results when compared head-to-head to crizotinib for NSCLC has also had promising results in preclinical neuroblastoma models." (PMID 30326621, 2018). "ALK TK activation mechanisms in neuroblastoma are not limited to ALK amplification." (PMID 29495603, 2018). "Furthermore, while heparins with short chain lengths are not able to activate anaplastic lymphoma kinase (ALK), heparins with longer chain lengths can induce dimerization and activation ALK in neuroblastoma cells." (PMID 30425976, 2018). "Altogether, these data suggest that ALK inhibition alone is not sufficient to achieve durable and deep responses in neuroblastoma tumors that contain ALK aberrations, and that a combination therapy that consists of an ALK inhibitor and a second agent is required." (PMID 28425916, 2017). "We selected 15 neuroblastoma cell lines previously reported to harbor MYCN and/or ALK amplifications, gains or the normal diploid chromosomal complements in the regions of MYCN and ALK as a panel in which to validate detection of gene amplification or gain by ddPCR." (PMID 29156716, 2017). "Similarly, single treatment with crizotinib in human neuroblastoma xenograft models expressing ALK­-addicted cell lines reduces tumor growth but does not substantially debulk or eradicate tumors." (PMID 27483357, 2016). "Given many of the altered genes in neuroblastoma, like ALK, have important roles in development of non-tumor cells, targeting other tumor-specific vulnerabilities could potentially reduce late effects from treatment." (PMID 28035989, 2016). "However, a recent clinical trial revealed that not all neuroblastoma patients with aberrant ALK activation respond to Crizotinib." (PMID 27732954, 2016). "Recent identification of the ALK ligands FAM150A and FAM150B, which potently activate ALK signaling, raises the possibility that ALK activity may be important in non-ALK mutant neuroblastoma cases." (PMID 27483357, 2016). "Thus, PF-06463922 inhibits ALK activity in neuroblastoma cell lines dependent on ALK activity with high affinity and a lack of toxicity at the cellular level." (PMID 27483357, 2016). "It is unclear whether this failure to achieve therapeutic benefit is related to the reduced affinity of crizotinib for the ATP-binding pocket of oncogenically activated ALK mutants, the overexpression of MYCN often observed in neuroblastoma, or a combination of these and other factors." (PMID 27483357, 2016). "Cell sensitivity to the peptide was dependent on ALK expression by tumor cells as: (i) ALK-negative tumor cells failed to respond and (ii) expressing either NPM–ALK or full-length ALK restored P36-responsiveness of lymphoma or neuroblastoma cells, respectively." (PMID 25950466, 2015). "A 6-year-old female was diagnosed with INSS high-risk stage 4 neuroblastoma with primary adrenal mass and bone metastases that included skullcap, lymph nodes, and the bone marrow, unfavorable histology, MYCN non-amplified, and ALK with no detectable abnormal mutations." (PMID 40286729, 2025). "Stratifying eligible neuroblastoma patients for ALK.CAR‐T therapy could use the ALK genetic status and expression levels as a biomarker; nonetheless, the majority of neuroblastoma patients could benefit from this combination therapy irrespective of their ALK genetic status." (PMID 38877641, 2024). "This was because heparin triggered ALK phosphorylation in neuroblastoma (NB) cells, but it failed to activate ALK in 3T3 cells." (PMID 37892172, 2023). "As no additional alteration in genes associated with neuroblastoma or CCHS could be detected, we suggest that the ALK F1174I mutation may not only predispose to congenital multifocal neuroblastoma but could also have contributed to the respiratory dysfunction seen in this patient." (PMID 36140661, 2022).
neuroblastoma (continued). "As ALK inhibition by crizotinib abolished the effect of the HDAC8 inhibitor on AKT but strongly inhibited ERK, which resulted in enhanced cell death, we hypothesized that RTK inhibition shifts the HDAC8 inhibitor-mediated differentiation phenotype toward neuroblastoma cell death." (PMID 29515255, 2018). "A neuroblastoma-specific panel using NGS could be developed to identify more comprehensive genomic information to molecularly treat and predict prognosis with sophistication based on genomic characteristics such as MYCN, TERT, ATRX, ALK, ARID1, and telomere length." (PMID 28521285, 2017). "SH-SY5Y neuroblastoma cell lines could not be representative to all the neuroblastoma cells bearing ALKF1174L mutation, and further studies of ALK phosphorylation with larger neuroblastoma samples and neuroblastoma cell lines will be required to confirm our results." (PMID 22479414, 2012). "Although it is not yet known if this interaction contributes to neuroblastoma disease pathogenesis, it is intriguing that the interaction occurs at the promoter regions of several genes important for the development of neuroblastoma, including ALK, AURKA and BDNF." (PMID 21731748, 2011). "ALK RNA TPM in all normal tissues (n = 17,382 across 31 tissues) were less than neuroblastoma and was generally absent other than in the pituitary (3.53, n = 283) and testis (3.08, n = 361)." (PMID 40813394, 2025). "Although several ALK tyrosine kinase inhibitors (TKI) have been evaluated, to date none have been approved for clinical use in patients with neuroblastoma." (PMID 38032104, 2023). "Tumour growth was stunted by trametinib in N-Ras mutant (Q61K) neuroblastoma and EML4-ALK fusion-positive NSCLC xenografts, but not in the ALK-addicted neuroblastoma tumours." (PMID 37414143, 2023). "To identify genes mediating an ALK inhibitor-resistant phenotype in neuroblastoma cells, we performed a genome-wide CRISPR-Cas9-based knockout screen in neuroblastoma cells incubated in the presence or absence of ALK inhibitors." (PMID 35689207, 2022). "However, it is not known if the reciprocal could occur with ALK signaling affecting PHOX2B levels and thereby also cause perturbation of neuronal differentiation during specific developmental windows and give rise to neuroblastoma and a CCHS-like condition." (PMID 36140661, 2022). "In the present study we show that the exposure to the HDAC inhibitors entinostat and valproic acid markedly enhanced p75NTR expression in different human neuroblastoma cell lines in a manner that was apparently independent of NMYC and ALK genotypes." (PMID 35409209, 2022). "Neither alectinib nor crizotinib were able to inhibit growth of non-ALK addicted CLB-PE and IMR-32 neuroblastoma cell lines, suggesting that neither alectinib nor crizotinib was toxic at the levels employed." (PMID 31334113, 2019). "In contrast to ALK-negative cells, ALK-positive ALCL and neuroblastoma cells responded to P36 in a dose-dependent manner, showing a decrease of the number of viable cells compared with their untreated control counterpart." (PMID 25950466, 2015). "However, the feasibility and efficacy of ALK and SHP2 inhibitor combinations for neuroblastoma has not been assessed." (PMID 38032104, 2023). "However, drug resistance against ALK inhibitors and the absence of direct antagonists for MYCN limit the treatment of neuroblastoma in clinic." (PMID 36585695, 2022). "However, both non-neuroblastoma control lines (RD and VH7) expressed c-MET while ALK expression was not detectable." (PMID 29515255, 2018).
neuroblastoma (continued). "In contrast, ALK amplification was not a statistically independent marker for survival in models with MYCN, stage and age in a meta-analysis, combining a new series of 254 neuroblastomas and 455 published cases from 3 other cohorts." (PMID 29156716, 2017). "We validated our protocols in a panel of 15 neuroblastoma cell lines and 2 MYC-amplified non-neuroblastoma cell lines to control for assay specificity, and reveal evidence for different MYCN or ALK status than previously reported for 7 cell lines commonly used in research." (PMID 29156716, 2017). "We show complete maintained responses to CDX0239-PBD in NB-SD, COG-N-424x, and NGP, xenografts that do not harbor ALK gene amplification and exhibit ALK surface expression representative of the majority of neuroblastoma tumors and relevant xenograft models." (PMID 40813394, 2025).
lymphoma (301 papers, 2006 to 2025). A malignant (clonal) proliferation of B- lymphocytes or T- lymphocytes which involves the lymph nodes, bone marrow and/or extranodal sites. "Since ALK is predominantly expressed in a limited number of scattered neurons and is not detected in haematopoietic tissue postnatally, the presence of ALK expression in lymphoid cells serves as a diagnostic marker for ALK‐positive lymphoma." (PMID 40351161, 2025). "Specifically, in this lymphoma subtype, the ALK mutation is associated with a favorable prognosis and potential for targeted therapy with ALK inhibitors such as alectinib." (PMID 40699359, 2025). "The analysis confirmed that ALK+ lymphoma carry additional somatic mutations along with the driver translocation event: overall we found a median of 10 (interquartile range (IR) = 2–25) non-synonymous single nucleotide variants (SNVs) per patient." (PMID 39478125, 2024). "This lymphoma is caused by chromosomal translocations involving the anaplastic lymphoma kinase gene (ALK)." (PMID 35246138, 2022). "Some studies on ALK-mutated lymphomas have shown that ALK rearrangements lead to increased STAT3 signal transduction, which is involved in downstream signaling of inflammatory cytokines." (PMID 33996610, 2021). "BATF/BATF3 are important for expression of genes in ALK+ ALCL that are associated with the TH17/group 3 innate lymphoid cell gene signature observed in this lymphoma." (PMID 33413671, 2021). "In an ALK-positive lymphoma mouse model, DNA vaccines with plasmids encoding part of the ALK cytoplasmic domain effectively prevented the development of systemic and local lymphoma via specific CD8+T-cell cytotoxicity and interferon-γ response." (PMID 32059449, 2020). "We previously demonstrated that crizotinib induced cytoprotective autophagy in ALK+ lymphoma cells and that its further intensification was associated with cell death." (PMID 33066037, 2020). "The mechanisms behind ALK rearrangement and increased thrombotic risk in NSCLC are unclear but some studies in lymphomas with ALK mutations suggest the ALK rearrangement results in increased STAT3 signaling and inflammation." (PMID 32707653, 2020). "This is supported by the observation that the vaccination of B cell-deficient BALB/C mice with ALK plasmid DNA showed a protection against tumor growth and a cytotoxic T cell response after challenge with ALK-positive lymphoma cells." (PMID 29642597, 2018). "This mutation fuses the nucleophosmin (NPM) gene with the ALK gene and was first described in Ki-1 Lymphoma." (PMID 25888090, 2015). "Anaplastic lymphoma kinase (ALK) has been implicated in the growth of neoplastic cells in malignant lymphomas." (PMID 24520283, 2014). "ALK is best characterised via its relationship with lymphomas, caused by ALK gene fusion with any of several other housekeeping genes." (PMID 22254144, 2011). "ALK positive diffuse large B-cell lymphomas (DLBCL) are a distinct lymphoma subtype associated with a poor outcome." (PMID 21494621, 2011). "The anaplastic lymphoma kinase (ALK) has recently been implicated in growth of neoplastic cells in malignant lymphomas." (PMID 21297223, 2010). "In addition, the ATIC gene is associated with the risk of lymphoma progression in cases of ATIC protein fusion with the protein of oncogene ALK (anaplastic lymphoma kinase)." (PMID 35205374, 2022). "This not only provided important diagnostic and prognostic information since ALK-positive lymphomas have an improved outlook, but an important offshoot of this work was that the use of this antibody has opened up pathways to investigate tumor development and therapy." (PMID 35011737, 2022). "Another study showed that PDGFR inhibition was a rational and effective therapeutic agent for nucleophosmin-anaplastic lymphoma kinase (NPM-ALK) fusion lymphomas, suggesting that ALK might be a target of activating mutations of the genes encoding PDGFRA." (PMID 32005261, 2020).
lymphoma (continued). "In sum, our findings demonstrate that a well-known phenotypic characteristic of ALK+ ALCL may be an important factor underlying the ability to treat this lymphoma." (PMID 25168906, 2014). "This case highlights a rare presentation of ALK-positive ALCL masquerading as a recurrent axillary abscess, emphasising the diagnostic challenges of lymphoma presenting as an apparent soft-tissue infection." (PMID 41445989, 2025). "An ALK-1 immunostain should be performed on lymphomas with large cell morphology characterized by immunoblastic, plasmacytoid, or plasmablastic features in order to assess the likelihood of ALK-positive large B-cell lymphoma." (PMID 40428800, 2025). "CD20-negative aggressive lymphomas include plasmablastic lymphoma, primary effusion lymphoma, ALK-positive large B-cell lymphoma and HHV8-positive diffuse large B-cell lymphoma." (PMID 40869163, 2025). "Structure-based virtual screening discovered small-molecule allosteric inhibitors, which were tested in lymphoma cell models, including ALK and BTK-inhibitor resistant lines." (PMID 41154443, 2025). "The final diagnosis was anaplastic lymphoma kinase (ALK) positive lymphoma involving the left main stem bronchus." (PMID 41346922, 2025). "The first description of ALCL as a CD30‐positive lymphoma in 1985 was followed by the detection of chromosomal translocations involving the ALK gene at chromosome 2p23." (PMID 40351161, 2025). "TD-004 is also a PROTAC that targeted ALK and inhibited the growth of ALK fusion-positive lymphoma cell lines." (PMID 41226551, 2025). "Alternatively, researchers recently investigated the role of the Nuclear Interaction Partner of ALK (NIPA) in a specific type of lymphoma induced by the NPM-ALK gene." (PMID 38397899, 2024). "CALR expression over time was analyzed in ALK-positive lymphoma K299 cell line, showing that, even in this case, surface levels of CALR were reduced after long exposure to low-dose crizotinib (i.e., 120 nM), when compared to the untreated condition." (PMID 39767726, 2024). "Recently, Petrazzuolo and colleagues showed that anaplastic lymphoma kinase (ALK) inhibition causes immunogenic cell damage through the upregulation of CALR in a panel of ALK-driven lymphoma cell lines." (PMID 39767726, 2024). "When combined with chemotherapy, ALK-DNA vaccination significantly extended the survival of mice afflicted with ALK+ lymphomas." (PMID 38397899, 2024). "In a phase 1, open-label trial of oral TSR-011 in patients with advanced solid tumors and lymphomas, 6 of 14 patients with ALK-positive who were naive to ALK TKI experienced partial response." (PMID 38835344, 2024). "ALCL is a distinct subtype of lymphoma characterized by abnormal proliferation of lymphocytes and is divided into ALK-positive and ALK-negative subtypes." (PMID 38524078, 2024). "Hh is amplified in ALK positive lymphoma where silencing GLI inhibits growth of ALK driven lymphoma cells." (PMID 39056757, 2024). "Some other tumors, like lymphomas, upregulate PD-L1 via other pathways, including nucleophosmin/anaplastic lymphoma kinase (NPM/ALK), which activates PD-1 expression via the signal transmitter, transcription factor STAT3." (PMID 39534873, 2024). "While the establishment of an overt lymphoid malignancy is almost universally a stepwise process, lymphomas expressing anaplastic lymphoma kinase (ALK) and, seemingly, similarly powerful oncogenic kinases are a notable exception." (PMID 38638855, 2024). "NPM-ALK is a constitutively active fusion ALK in some lymphomas that enhances creation of transcription activating Gli-A." (PMID 39056757, 2024). "None have experimented BRIGATINIB (To note: a clinical trial, NCT04925609, is currently in progress to study the efficacy of BRIGATINIB in a population of under 25-year-olds with ALK rearrangement with lymphoma, IMT or others solid tumors)." (PMID 39931211, 2024).